LEF1 (lymphoid enhancer binding factor 1)
Diseases named in the same sentence as LEF1 in open-access papers (continued):
Sharing a sentence is not in itself a finding about the gene and the disease.
gastric tumors (2 papers, 2016 to 2023). "We therefore performed immunostaining of gastric tumors from iLgr5;GLI2A mice to assess Lef1 expression and nuclear translocation of β-catenin, markers of canonical Wnt signaling." (PMID 26859571, 2016).
hepatoblastoma (2 papers, 2024 to 2025). Hepatoblastoma (HB) is a malignant hepatic tumor and is the most common pediatric liver cancer. "In summary, based on the staining pattern for HNF4A and LEF1, we were able to unequivocally distinguish these two hepatoblastoma subtypes, while it was not evident with β-catenin staining alone." (PMID 39567475, 2024).
idiopathic pulmonary fibrosis (2 papers, 2011 to 2023). Idiopathic pulmonary fibrosis (IPF) is a nonneoplastic pulmonary disease that is characterized by the formation of scar tissue within the lungs in the absence of any known cause. "Further examination of lung tissue from patients with idiopathic pulmonary fibrosis, an age‐related disease with strong ties to cellular senescence, revealed a stark dysregulation of LEF1." (PMID 37961030, 2023). "Konigshoff and colleagues confirmed the up-regulation of WNT1, WNT7B and WNT10B, FZD2, FZD3, β-catenin, and LEF1 expression in the lungs of individuals with idiopathic pulmonary fibrosis compared to transplant donor lung." (PMID 21490961, 2011). "Due to the important role aging and cellular senescence play in the pathophysiology of idiopathic pulmonary fibrosis (IPF), we checked LEF1 expression in lung tissue from Normal/Healthy and IPF lung donors." (PMID 37961030, 2023).
ischemia (2 papers, 2017 to 2023). A hypoperfusion of the BLOOD through an organ or tissue caused by a PATHOLOGIC CONSTRICTION or obstruction of its BLOOD VESSELS, or an absence of BLOOD CIRCULATION. "Since previous studies have reported that fibrinogen treatment increases Lef1 expression in OPCs,6 we used an in vitro model of ischemia induced by OGD." (PMID 36756722, 2023). "Some of these regulators have been already associated with different forms of ischemia (e.g. Creb, Stat1, Bcl6, miR-122, miR-21, miR-214, miR-493) while others have not (e.g. Maf, Nptx1, Lef1, miR-290, miR-297, miR-466)." (PMID 29121052, 2017).
lupus (2 papers, 2025). "Levels of anti-dsDNA antibodies and various kidney injury markers were upregulated, suggesting that the LEF-1 inhibitor effectively aggravates lupus symptoms in KO mice." (PMID 40467564, 2025). "Through differential gene enrichment analysis (| logFC | > 1, P < 0.05), our results suggest that LEF1 may influence immune response pathways, including systemic lupus erythematosus, the interleukin-2 signaling pathway, and type II interferon signaling, by regulating associated genes." (PMID 40918098, 2025). "Results confirmed elevated methylation levels at CpG sites in the LEF-1 promoter regions in B cells from SLE patients and lupus model mice compared to healthy individuals and normal mice." (PMID 40467564, 2025). "LEF-1 inhibitors in MBD2 knockout mice induced significant lupus-like symptoms, highlighting the critical role of LEF-1 in SLE pathogenesis." (PMID 40467564, 2025). "To verify whether the elevated levels of IFN-α in lupus contribute to the hypermethylation of Lef-1, we stimulated mouse splenic B cells with IFN-α for 24 h, and found increased methylation levels at the CpG site in the Lef-1 promoter region." (PMID 40467564, 2025).
mental disorder (2 papers, 2013 to 2019). A disease that has its basis in the disruption of mental process. "Recently, studies show that mutations in components of β-catenin signaling networks have been associated with several psychiatric disorders, indicating the involvement of β-catenin and LEF1/TCF proteins in the proper functioning of the brain." (PMID 23152144, 2013). "Altogether, genetic alterations in individuals with mental disorders and behavioral deficits in genetically modified animals have provided convincing evidence that the canonical Wnt/β‐catenin pathway and LEF1/TCFs (particularly TCF7L2) are involved in the pathogenesis of mental disorders." (PMID 31218672, 2019).
Obesity (2 papers, 2021 to 2022). Accumulation of substantial excess body fat. "This was consistent with previous studies on Lef1/β-catenin (Wnt signaling pathway) regulating fat deposition in obesity." (PMID 36611960, 2022).
osteoporosis (2 papers, 2024 to 2025). A condition of reduced bone mass, with decreased cortical thickness and a decrease in the number and size of the trabeculae of cancellous bone (but normal chemical composition), resulting in increased fracture incidence. "Interestingly, the predicted transcription factors regulating TRAV140, Fosl1(+), and Lef1(+), represented promising therapeutic targets for age-related bone disorders like osteoporosis." (PMID 39436962, 2024).
periodontitis (2 papers, 2019 to 2023). An acute or chronic inflammatory process that affects the tissues that surround and support the teeth. "Periodontitis tended to reduce the expression of LEF-1 and drastically reduced TCF-7 expression in wildtype littermates." (PMID 31921182, 2019). "During periodontitis, the expression levels of LRP6, β-catenin, and LEF1 were suppressed in the inflammatory microenvironment." (PMID 37244994, 2023).
prostate tumor (2 papers, 2013 to 2017). "In particular, we found primarily overexpression of CTNNB1, CDH1, SMAD2, SMAD3, TCF3, LEF1 in younger patients and overexpression of SNAI1 and underexpression of KRT5, KRT19, OCLN, CDH2 and MUC1 which clearly indicates different characteristics of prostate tumor in younger vs older patients." (PMID 29206234, 2017). "In addition, in Pten null prostate tumours there is an increase in the active non-phosphorylated stabilized form of β-Catenin, which is thought to be involved in the transcription of target genes, although we could not detect an induction of LEF1." (PMID 23300485, 2013).
psoriasis (2 papers, 2021 to 2025). An autoimmune condition characterized by red, well-delineated plaques with silvery scales that are usually on the extensor surfaces and scalp. "The LEF1 mRNA expression was 2.3-fold lower in lesional skin of patients with psoriasis (p < 0.001) and 2.0-fold lower in psoriasis non-lesional skin (p < 0.01) compared with healthy control subjects." (PMID 34884858, 2021). "In psoriasis uninvolved skin, positive correlations were found between the expression levels of CREB1 and LEF1 (r = 0.66, p < 0.05), USF1 and PNOC (r = 0.81, p < 0.05), MITF and ATRN (r = 0.58, p < 0.05), MITF and NURR1 (r = 0.56, p < 0.05) and MITF and MAPK14 (r = 0.75, p < 0.01)." (PMID 34884858, 2021). "LEF1 expression level was decreased in psoriasis lesional and non-lesional skin compared with healthy control skin." (PMID 34884858, 2021).
renal carcinoma (2 papers, 2022). A carcinoma arising from the epithelium of the renal parenchyma or the renal pelvis. "TGFB1 has enhanced the proliferation and metastatic potential of renal carcinoma by upregulating lymphoid enhancer-binding factor 1/integrin αMβ2." (PMID 35222525, 2022). "For example, TGF-β1 enhances the proliferation and metastatic potential of RCC cells by upregulating lymphoid enhancer-binding factor 1/integrin αMβ2, and MUC12 relies on TGF-β1 signaling to mediate the growth and invasion of renal cancer cells." (PMID 36186427, 2022).
renal fibrosis (2 papers, 2019 to 2022). A final common manifestation of a wide variety of chronic kidney diseases characterized by glomerulosclerosis and tubulointerstitial fibrosis. "Numerous Wnt/β-catenin target genes (c-Myc, twist, lymphoid enhancer-binding factor 1, and snail) were induced, leading to the EMT program and renal fibrosis." (PMID 35311469, 2022). "Furthermore, it is known that renal injury has a close relationship with the development of renal fibrosis and, during this process, tubular epithelial cells in the kidney undergo EMT via upregulating β-catenin/lymphoid enhancer-binding factor 1 (LEF1) signaling and MMP-7." (PMID 31417401, 2019).
sarcoma (2 papers, 2012). A usually aggressive malignant neoplasm of the soft tissue or bone. "As revealed by the MMMT photomicrograph, Lef1 expression was largely confined to the adenocarcinoma or glandular portions of the tumors, and not present in the sarcoma and stromal areas." (PMID 22792274, 2012). "Genes including Wnt 4 and 5a, beta-catenin, LEF1, and RhoA in Wnt-signaling pathways showed significantly lower expression and DKK1, a Wnt signal inhibitor showed strong expression in both sarcomas, while those in Hedgehog pathways showed higher expression in both sarcomas, especially Gli1." (PMID 22852096, 2012).
skin cancer (2 papers, 2014 to 2019). "In mice overexpressing mutant Lef1, Gata6 ablation increases the total number of skin tumors yet decreases the proportion of SG tumors." (PMID 30886049, 2019).
synovial sarcoma (2 papers, 2020 to 2021). "In EWS, synovial sarcoma (SS), OS, and to a lesser extent in LMS, a high level of Wnt activation, scored by the nuclear localization of β-catenin or LEF-1, is associated with a poor clinical outcome." (PMID 34294128, 2021). "Several other genes pertaining to these networks may be dysregulated in synovial sarcoma, including LEF1, AXIN2, TCF7, and FZD homologues in the Wnt/β-catenin, HES1, and NOTCH1 in the Notch, as well as SMO and PTCH in the Sonic Hedgehog pathways." (PMID 32322158, 2020).
T-cell acute lymphoblastic leukemia (2 papers, 2017 to 2023). Acute lymphoblastic leukemia of T-cell origin. "Depending on the context, LEF1 loss can also be harmful, since in some cases, such as in T-cell acute lymphoblastic leukemia, this gene acts by repressing MYC transcription." (PMID 36768749, 2023). "This is similar to T-cell acute lymphoblastic leukemia, in which LEF1-inactivated cases show increased levels of MYC expression when compared with cases with intact LEF1." (PMID 27965462, 2017).
adenomyosis (1 paper, 2025). The growth of endometrial tissue inside the muscular wall of the uterine corpus. "Reduced lymphoid enhancer-binding factor 1 (LEF1) expression in patients with adenomyosis during the mid-secretory phase leads to impaired endometrial receptivity, affecting embryo implantation." (PMID 39794729, 2025). "In the adenomyosis mouse model, we observed a decrease in LEF1 expression and a reduction in implantation sites compared to control mice, accompanied by impaired decidualization and receptivity." (PMID 39794729, 2025). "Simultaneously, the decreased expression of LEF1 in the endometrial stromal cells of adenomyosis mice aligns with the findings observed in patients with adenomyosis." (PMID 39794729, 2025). "This research provides insights into one potential molecular mechanism underlying this decreased receptivity, with a specific focus on the reduced expression of LEF1 in the endometrial stromal cells during the mid-secretory phase in adenomyosis patients." (PMID 39794729, 2025). "Western blot and quantitative real-time polymerase chain reaction (RT-qPCR) analyses revealed that patients with adenomyosis showed a marked decrease in LEF1 expression in the stromal cells of the endometrium during the mid-secretory phase." (PMID 39794729, 2025). "Transcriptome sequencing, dual-luciferase reporter assays, and chromatin immunoprecipitation (ChIP) experiments showed that LEF1 could bind to the promoter region of interleukin (IL)-11 and promote its transcription, and IL-11 expression was also found to be downregulated in adenomyosis patients." (PMID 39794729, 2025).
adrenocortical tumours (1 paper, 2024). "Of note, in the two samples with an abundance of AC1, we have observed a high expression of AFF3, ISM1 and LEF1, all known CTNNB1 target genes in both benign and malignant adrenocortical tumours." (PMID 39167619, 2024).
aortic aneurysm (1 paper, 2025). A ruptured aneurysm located in the wall of the proximal portion of the descending aorta proceeding from the arch of the aorta. "Beyond its role in VSMCs, LEF1 may also engage in crosstalk with endothelial cells, thereby influencing the progression of aortic aneurysms." (PMID 41208012, 2025).
atrial septal defect (1 paper, 2025). Interauricular communication is a congenital malformation characterized by a communication between the atrial chambers of the heart. "In the atrial septum, we identified a distinct endocardial cushion-related population marked by strong LEF1 and MSX1 expression, supporting a potential causal role for these transcription factors in atrial septal defects." (PMID 41162788, 2025).
B cell lymphoma (1 paper, 2022). "In mouse CD1d– ATA B cell lymphoma, we observed reduced LEF-1 and increased IL-6 and Arid5a." (PMID 36050343, 2022). "The strong ATA B cell lymphoma stages in mice were CD1d–, LEF-1–, and IL-6+ with increased Arid5a." (PMID 36050343, 2022).
bone sarcoma (1 paper, 2015). A sarcoma that arises from the bone. "We have detected upregulated canonical Wnt activity relative to that observed in hMSCs, as evidenced by increased levels of active β-catenin, LEF1, TCF transcriptional activity and downstream target gene c-Myc in all bone sarcoma cell lines." (PMID 25999350, 2015).
brain inflammation (1 paper, 2025). "Furthermore, adoptive transfer of B-1 cells lacking TCF1 and LEF1 fails to suppress brain inflammation." (PMID 40836098, 2025).
brain tumor (1 paper, 2023). "To compare the data quality of RRST and standard Visium datasets obtained from the pediatric brain tumor samples, we examined the expression of WNT-signaling genes, including AXIN2, DKK4, LEF1 and CTNNB1 and two known targets of the WNT pathway SP5, GAD122,23." (PMID 36720873, 2023).
Burkitt lymphoma (1 paper, 2023). A rare form of malignant mature B-cell non-Hodgkin lymphoma. "In this study, hTERT-immortalized normal oral keratinocytes (NOK) and Burkitt Lymphoma cells latently infected with EBV were investigated to determine the role of Wnt signaling effector LEF1 in the EBV life cycle." (PMID 38113273, 2023).
cardiomyopathy (1 paper, 2016). A disease of the heart muscle or myocardium proper. "Some DEGs related to cytoskeleton organization (e.g. MTSS1, ACTN4 and CALD1), cardiomyopathy (e.g. ITGB5) and immune response (e.g. C1S and C1R), as well as some regulators (e.g. LEF1 and hsa-miR-33a) might play pivotal roles in the progression of DN." (PMID 27613243, 2016).
cholangiocarcinoma (1 paper, 2025). A carcinoma that arises from the intrahepatic biliary tree (intrahepatic cholangiocarcinoma) or from the junction, or adjacent to the junction, of the right and left hepatic ducts (hilar cholangiocarcinoma). "Furthermore, correlation analysis using cholangiocarcinoma datasets from The Cancer Genome Atlas (TCGA-CHOL) showed that WNT pathway genes (AXIN2, CTNNB1, LEF1) positively correlated with TIC signature genes (KIT, SALL4, CD44, SOX2)." (PMID 39774471, 2025).
chordoma (1 paper, 2023). Chordomas are rare malignant tumors arising from embryonic remnants of the notochord in axial skeleton. "Additionally, CD4 T‐cell clusters had widespread overexpression of naïve markers (CCR7, SELL, LEF1 and TCF7), suggesting that CD4 T cells were in a naïve state in chordoma." (PMID 37784253, 2023).
classic Hodgkin lymphoma (1 paper, 2023). Classical Hodgkin lymphoma (CHL) is a B-cell lymphoma characterized histologically by the presence of large mononuclear Hodgkin cells and multinucleated Reed-Sternberg (HRS) cells. "A recent review examined the expression of LEF1 in a group of 117 Hodgkin lymphomas, which consisted of 66 cases of classic Hodgkin lymphoma (CHL), 27 cases of nodular lymphocyte-predominant Hodgkin lymphoma (NLPHL), and 24 cases of Richter transformation of CLL/SLL to CHL." (PMID 38179383, 2023).
colon adenoma (1 paper, 2024). An adenoma that arises from the colon. "However, an in vivo study published in Science showed that LEF1 restricts ectopic crypt formation and tumor cell growth in colon adenomas from APC-deficient mice." (PMID 39200196, 2024).
colorectal adenocarcinoma (1 paper, 2024). The most common type of colorectal carcinoma. "LEF1 is overexpressed in colorectal adenocarcinoma and is associated with the occurrence and progression of multiple tumors." (PMID 38824174, 2024).
cylindromas (1 paper, 2014). "Strong nuclear staining of protein from both Notch target genes LEF1 and RUNX1 were observed in cylindromas, spiradenomas and trichoepitheliomas." (PMID 25565632, 2014).
ductal carcinoma (1 paper, 2025). "To investigate the functional importance of LEF1 expression in CAFs, we depleted LEF1 in the exp‐CAFs and subcutaneously implanted them along with breast ductal carcinoma MCF10DCIS.com cells into immunodeficient mice." (PMID 39887653, 2025). "Notably, LEF1‐positive CAFs were more prevalent in SCC compared to ductal carcinoma." (PMID 39887653, 2025). "Moreover, we observed a significantly higher proportion of LEF1‐positive fibroblasts in the cancerous stroma in SCC (average: 57.9%) compared to ductal carcinoma cases (average: 31.5%)." (PMID 39887653, 2025).
endometrioid tumor (1 paper, 2012). A benign, borderline, or malignant epithelial tumor of the female reproductive system characterized by the presence of glands and/or cysts lined by neoplastic cells that resemble endometrial cells. "Lef1 mRNA was expressed at higher levels in endometrioid tumors than in papillary serous tumors and MMMT, and was expressed at higher levels in tumors of grades 1 and 2 than in those of grade 3." (PMID 22792274, 2012). "Lef1 expression also differed significantly (p<0.05) between grade 1–2 and grade 3 endometrioid tumors." (PMID 22792274, 2012).
endothelial dysfunction (1 paper, 2025). In vascular diseases, endothelial dysfunction is a systemic pathological state of the endothelium (the inner lining of blood vessels) and can be broadly defined as an imbalance between vasodilating and vasoconstricting substances produced by (or acting on) the endothelium. "For example, silencing of endothelial vWF has been shown to reduce angiotensin II–induced endothelin‐1 expression, suggesting that a LEF1‐vWF‐ET‐1 axis might contribute to endothelial dysfunction in AAA." (PMID 41208012, 2025).
familial cancers (1 paper, 2021).
fibrosarcoma (1 paper, 2007). A malignant mesenchymal fibroblastic neoplasm affecting the soft tissue and bone. "Golub-score analysis identified a relatively poor discriminatory signal of 200 genes for the fibrosarcomas, which regardless of high FDR contained several of the upregulated genes previously associated with fibrosarcoma, e.g. BMI1, H1F0, LEF1, RBM4, ITM2A, IGFBP2 and PTGS2." (PMID 17359542, 2007).
HCMV infection (1 paper, 2012). "The TCF/LEF-1-luciferase reporter construct TOPflash was used to determine whether HCMV infection affects β-catenin activity." (PMID 23071438, 2012).
head and neck cancer (1 paper, 2023). A primary or metastatic malignant neoplasm affecting the head and neck. "Considering that LEF1 is associated with histone modification and that the KDM4 subfamily of histone-modifying enzymes is dysregulated in OSCC, we analysed the expression of LEF1 and KDM4s (KDM4A–D) using The Cancer Genome Atlas (TCGA) Head and Neck Cancer dataset." (PMID 37553362, 2023).
herpesvirus infection (1 paper, 2025). "During Kaposi’s sarcoma-associated herpesvirus infection, the virus-encoded vIRF1 protein activates the transcription of the host cell circARFGEF1 by binding to the transcription factor LEF1." (PMID 41300734, 2025).